BARD1 (BRCA1 associated RING domain 1)
Diseases named in the same sentence as BARD1 in open-access papers (continued):
Sharing a sentence is not in itself a finding about the gene and the disease.
pulmonary fibrosis (2 papers, 2015 to 2025). Chronic progressive interstitial lung disorder characterized by the replacement of the lung tissue by connective tissue, leading to progressive dyspnea, respiratory failure, or right heart failure. "As uncontrolled growth is also the feature of lung fibrosis, BARD1 expression was expected to be associated with lung fibrosis." (PMID 26415510, 2015). "We report here for the first time that the tumor suppressor BARD1 and its pro-proliferative isoform BARD1β are associated with pulmonary fibrosis and presumably involved in its pathogenesis." (PMID 26415510, 2015). "To evaluate the association of BARD1 with human lung fibrosis, we investigated its expression in lung biopsies from patients with pulmonary fibrosis." (PMID 26415510, 2015). "This could be due to the switching of the splicing pattern of the BARD1 gene that is associated with lung fibrosis, which would need other approaches for detection than screening for mutations or overall expression changes." (PMID 26415510, 2015). "It is therefore possible that SNPs in BARD1 might be found associated with specific subclasses of lung fibrosis." (PMID 26415510, 2015). "The data presented here confirm that TGF-β induces BARD1 expression and demonstrate for the first time that this occurs in lung fibrosis." (PMID 26415510, 2015). "To determine the specific expression of FL BARD1 and/or BARD1 isoforms on the mRNA level, we performed RT-PCR on RNA extracted from lung biopsies from patients with pulmonary fibrosis (n = 17) and controls." (PMID 26415510, 2015). "Previous reports have shown that BARD1 expression is upregulated in response to hypoxia and associated with TGF-β signaling, both recognized factors driving lung fibrosis." (PMID 26415510, 2015). "BARD1 could act as a downstream activator in EC apoptosis and fibroblast proliferation, making it a critical target for therapeutic intervention in pulmonary fibrosis treatment." (PMID 40901482, 2025). "As hypoxia is thought to also act as driver of lung fibrosis, we investigated whether BARD1 expression was modified by hypoxia in lung fibrosis." (PMID 26415510, 2015). "Based on the key properties of BARD1 and its isoforms, and the observed features that characterize pulmonary fibrosis, we hypothesized that full length (FL) BARD1 and/or its isoforms might play a role in this disease." (PMID 26415510, 2015). "Loss of FL BARD1 leads to genetic instability, a hallmark of cancer cells, but not so much of lung fibrosis." (PMID 26415510, 2015). "The BARD1 gene was not discovered as one associated with lung fibrosis in previously reported genetic screens." (PMID 26415510, 2015). "We thus investigated whether BARD1 expression in lung tissues from mice with bleomycin induced lung fibrosis reflected the expression pattern observed in vitro and whether it paralleled the progression of the disease in this model." (PMID 26415510, 2015). "We therefore hypothesized that BARD1 and/or its isoforms might play a role in lung fibrosis." (PMID 26415510, 2015). "We investigated BARD1 expression as a function of TGF-β in cultured cells, in mice with experimentally induced lung fibrosis, and in lung biopsies from pulmonary fibrosis patients." (PMID 26415510, 2015). "We also analyzed BARD1 expression in lung tissues from patients with IPF and those of mice following experimentally induced lung fibrosis." (PMID 26415510, 2015). "We suggest that BARD1 might act as downstream activator of epithelial cell apoptosis and fibroblast proliferation and therefore might present a strong candidate target molecule for the treatment of lung fibrosis and possibly other diseases in which fibro-proliferation is a feature." (PMID 26415510, 2015).
uterine tumors (2 papers, 2020). "For example, the Q564H mutation of BARD1 found in ovarian, breast, and uterine tumors, reduces the BARD1-CstF-50 interaction, and prevents their inhibition of polyadenylation." (PMID 32708251, 2020). "Sequencing of cloned BARD1 mRNA transcripts from ovarian and uterine tumour tissues revealed only the variant allele." (PMID 32726901, 2020). "In a targeted sequencing analysis of 168 BC, OC, and uterine tumours, the first BARD1 variant, c.1692G>C; p.Gln564His, was identified in a woman diagnosed with a clear cell histopathological subtype of OC at the age of 73 years." (PMID 32726901, 2020).
Alzheimer disease (1 paper, 2025). A progressive, neurodegenerative disease characterized by loss of function and death of nerve cells in several areas of the brain leading to loss of cognitive function such as memory and language. "Using brain tissue from pure LBD, LBD with Alzheimer disease (AD) co-pathology (LBD-AD), and control cases, the immunohistochemical distributions of BRCA1, pBRCA1, its binding partner BARD1, and 53BP1 were examined." (PMID 39907307, 2025).
ataxia telangiectasia (1 paper, 2017). Ataxia-telangiectasia is the association of severe combined immunodeficiency (affecting mainly the humoral immune response) with progressive cerebellar ataxia. "Seven of these patients were found to carry two pathogenic variants including one biallelic ATM carrier with a clinical diagnosis of ataxia-telangiectasia, two ATM/BRCA2 carriers, one BRIP1/BRCA2 carrier, one BRCA1/CHEK2 carrier, one BARD1/PALB2 carrier, and one CHEK2/PALB2 carrier." (PMID 28008555, 2017).
brain tumors (1 paper, 2024). "BARD1 also trended with worse outcome in pediatric brain tumors." (PMID 38442712, 2024).
familial breast cancer (1 paper, 2019). "Variants that affect binding between BRCA1 and BARD1 have been linked to familial breast cancer or are non-functional in the HDR assay." (PMID 30925164, 2019).
gastric tumor (1 paper, 2023). "In addition, gastric tumor cells exhibited evident DNA damage and DNA repair defect, supported by downregulation of well-known genes involved in DNA damage and repair response, including RAD51, BRAC1, BRCA2 and BARD1." (PMID 36755269, 2023).
Hepatic hemangioma (1 paper, 2017). A congenital vascular malformation in the liver composed of masses of blood vessels that are atypical or irregular in arrangement and size. "BARD1 expression was initially detected in HCC samples, adjacent normal liver tissues, and normal liver tissues from hepatic hemangiomas surrounding the liver tissues by qRT-PCR and IHC." (PMID 28794477, 2017).
Infertility (1 paper, 2025).
large cell carcinoma (1 paper, 2020). A malignant epithelial neoplasm composed of large, atypical cells. "IHC staining analyses of 54 NSCLC tumors using antibodies that detect antigens mapped to exon 1 and exon 11 of BARD1 showed the highest expression of BARD1 in large cell carcinoma followed by squamous cell carcinoma then adenocarcinoma." (PMID 32708251, 2020).
liver cirrhosis (1 paper, 2025). "A report showed that BARD1 gene hypomethylation (13.3%) was more prevalent in patients with liver cirrhosis‐induced HCC than in normal controls." (PMID 39865406, 2025).
metastatic tumors (1 paper, 2020). "The results showed that patients with high-risk and metastatic tumors have reduced FL BARD1 expression." (PMID 32047556, 2020).
myopia (1 paper, 2021). "Upregulation of the BARD1 pathway in the first 6 h of normal light conditions highlights that prolonged occlusion, profound myopia and the morphologically thinned choroid is persistently physiologically stressful to cellular function." (PMID 33674625, 2021). "The presence of BARD1 post profound FDM may be an early indicator of the types of cellular damage observed in human and animal myopia, especially with regard to thinning of the choroid and retina." (PMID 33674625, 2021).
ovarian tumors (1 paper, 2021). "Interestingly, its presence was not restricted to HBOC patients, as one would expect considering the association of BARD1 with breast and/or ovarian tumors." (PMID 34824355, 2021).
pancreatic NEN (1 paper, 2020). "Although the susceptibility to PDAC and pancreatic NEN in patients with rare germline mutations in BARD1 remains to be studied, familial inheritance patterns and research evidence suggest that BARD1 may disrupt HR as mutations in BRCA2 and other DDR genes have also been shown to be tumorigenic." (PMID 32708251, 2020).
papillary thyroid carcinoma (1 paper, 2024). "Another patient, with PHEO, papillary thyroid carcinoma and colonic polyps, had a VUS of BARD1 (c.1333G > A)." (PMID 39673085, 2024).
pediatric cancer (1 paper, 2021). "The data on BARD1 significance in childhood cancer is limited." (PMID 33530592, 2021).
peritoneal carcinoma (1 paper, 2021). A peritoneum cancer that is located in the inside of the abdomen. "In family 1, the proband’s cousin was diagnosed with peritoneal carcinoma (PC) at age 73 and harbored the same BARD1 PV." (PMID 33498765, 2021).
prostate tumors (1 paper, 2022). "We next examined mutational signatures of HR deficiency in PALB2- and BARD1-mutant prostate tumors." (PMID 35768576, 2022).
pulmonary diseases (1 paper, 2019). "A number of these genes have reported associations with COPD or other pulmonary diseases and include; CYP2E1, HEY1, SMAD3, BARD1 and FOXP1." (PMID 31860681, 2019).
schizophrenia (1 paper, 2014). A major psychotic disorder characterized by abnormalities in the perception or expression of reality. "It indicates that BARD1 signaling pathway dysfunction may represent a novel susceptibility pathway for schizophrenia." (PMID 25522158, 2014). "BARD1 signaling pathway contains three under-expressed genes, BARD1, PCNA and UBE2L3, in which UBE2L3 polymorphism is associated with schizophrenia, and polymorphism study reveals that BARD1 is risk allele for schizophrenia." (PMID 25522158, 2014).
serous ovarian cancers (1 paper, 2019). "Approximately 50% of high-grade serous ovarian cancers are characterized by HR deficiency, which involves mutations in BRCA1/2, the MRN complex (MRE11, RAD50, NBS1), ATM, RAD51C/D, PALB2, BRIP1, BARD1, and other genes." (PMID 31572446, 2019).
soft tissue sarcoma (1 paper, 2021). A malignant neoplasm arising from muscle tissue, adipose tissue, blood vessels, fibrous tissue, or other supportive tissues excluding the bones. "Lastly, we examined the expression of BARD1 (FL and β) in a small group of aggressive soft tissue sarcoma, RMS." (PMID 33530592, 2021).
uveal melanoma (1 paper, 2015). A melanoma derived from melanocytes of the uveal tract. "Inactivation of the BAP1 gene which codes for an enzyme that binds to BRCA1 and BARD1 in regulating the tumor suppressor complex has been described in up to 84% of class 2 uveal melanomas." (PMID 25874144, 2015).
yolk sac tumour (1 paper, 2021). "All analyzed GCTs expressed BARD1 FL, with statistically significant differences between the BARD1 FL expression in the tumour (0.005 ± 0.004) and adjacent tissue (0.008 ± 0.0042) in the yolk sac tumour (YCT) (Z = 2.19; p = 0.024)." (PMID 33530592, 2021).
tumor (165 papers, 2008 to 2026). "BARD1 stands for BRCA1-associated RING domain protein-1 and contributes to tumor suppression by promoting apoptosis and DNA double-strand repair." (PMID 41528496, 2026). "Having validated that the variant effects measured by SGE are relevant to BARD1’s function as a tumor suppressor, we sought to rationalize the impact of missense variants in BARD1 on the basis of known structural features." (PMID 41282735, 2025). "BARD1, a tumor suppressor in concert with the breast cancer susceptibility gene BRCA1, plays a significant role in BRCA1-driven tumor suppression." (PMID 40901482, 2025). "BARD1 (BRCA1-Associated RING Domain 1) plays a complex role in tumor biology, functioning either as a tumor suppressor or as an oncogenic driver, depending on isoform expression, cellular context, and regulatory environment." (PMID 41009605, 2025). "In the following section, we will review mechanisms that influence the tumor suppressor functions of BARD1, including select mutational events that affect isoform expression, protein stability, and DNA repair activity." (PMID 41009605, 2025). "The main tumor susceptibility genes in CBC3T-1 cells included BARD1, KDR, FAT1, HNF1A, BRCA2, FANCA, and BRCA1." (PMID 37966669, 2024). "Allele-specific expression in RNA-seq indicates bi-allelic loss of BARD1 in tumor; however, the HRD score was below the threshold currently used for HRD classification in adult cancers." (PMID 37645774, 2023). "Knockdown of BARD1 in GBM cell lines reduces the invasive and value-added capacity of tumor cells, and thus BARD1-positively expressing malignant cells are a risk factor for GBM patients." (PMID 37727789, 2023). "On the other hand, low expression of RAD50/BARD1 in ERBB2-low cohort had a significant association with higher tumor stages (p = 0.013)." (PMID 37474724, 2023). "While the FL- BARD1, either individually or in complex with BRCA1, was reported to display a tumor suppressor function, BARD1 isoforms such as BARD1β and δ have an antagonistic effect on full-length BARD1, leading to cancer susceptibility and oncogenicity." (PMID 35650591, 2022). "BARD1 encodes a protein that regulates tumor suppression and cell growth, and interacts with the N-terminal region of BRCA1 (breast cancer gene 1)." (PMID 36430822, 2022). "Here, we demonstrate that additional hits to tumor DNA damage machinery, such as loss of BARD1 expression, can indeed render Ewing cells more sensitive to DNA-damaging agents, especially when in combination." (PMID 36187937, 2022). "One such candidate molecular factor is BARD1 (BRCA1 Associated RING Domain 1)—a tumour-suppressing gene involved in cell cycle control and genome stability, engaged in several types of adult-type tumours." (PMID 33530592, 2021). "Further studies in larger cohorts will be necessary to more precisely assess the BARD1-associated risk with this tumor phenotype." (PMID 33498765, 2021). "The breast cancer susceptibility protein BRCA1 and its partner BRCA1-associated RING domain protein 1 (BARD1) form an E3-ubiquitin (Ub) ligase complex that acts as a tumor suppressor in mitotic cells." (PMID 33593852, 2021). "SIGNIFICANCE STATEMENT BRCA1–BRCA1-associated RING domain protein 1 (BARD1) is an E3-ubiquitin (Ub) ligase complex acting as a tumor suppressor in mitotic cells." (PMID 33593852, 2021). "Mouse studies on BARD1 separation of function mutations have indeed shown that the role of fork protection in tumour formation is still under debate." (PMID 33755171, 2021). "Combined with the sequencing data, we also calculated the possible LOD score (3.0103, indicated significant) for the association of the BARD1-P24S/R378S variant with tumor occurrence within the HBOC pedigree." (PMID 33623049, 2021). "Full-length BARD1 (FL-BARD1) functions as a tumor suppressor, whereas aberrant splice variants, BARD1 isoforms, play an oncogenic role." (PMID 32722046, 2020).
tumor (continued). "BARD1 overexpression induces apoptosis, while the tumor-related mutation, Q564H, diminishes BARD1’s pro-apoptotic ability when exposed to genotoxic stress." (PMID 32708251, 2020). "Using tumor cells deficient for BARD1, a subunit of the BRCA1/BARD1 tumor suppressor complex, we have developed a new orthotopic model of triple‐negative breast cancer that spontaneously metastasizes to the lung and leads to systemic muscle deterioration." (PMID 32730698, 2020). "Genome-wide association studies (GWAS) in NB have shown that BARD1 acts as a tumor suppressor during its development and that certain variations in a single nucleotide have profound effects on BARD1 protein expression and NB susceptibility." (PMID 32708251, 2020). "Information regarding the hormone receptor (estrogen receptor [ER]/progesterone receptor [PR]) and human epidermal growth factor receptor 2 (HER2) status of the tumor was available for 20/23 BARD1-mutated index patients with BC." (PMID 31036035, 2019). "Recent data indicates that different splice variants transcribed from the BARD1 gene can have either tumor suppressing or oncogenic functions." (PMID 30760980, 2019). "We also showed that RNAP IIO ubiquitination was completely dependent on the presence of recombinant BRCA1/BARD1 and that the tumor-associated BRCA1 mutation C61G, which disrupts the RING domain, abolished RNAP IIO modification." (PMID 29180510, 2018). "In summary, we showed that BARD1 was significantly up-regulated in HCC tumor tissues and that BARD1 up-regulation was significantly associated with a lower HCC patient survival rate and advanced stage." (PMID 28794477, 2017). "PAR pathway is particularly interesting because of the promising drugs act on inhibiting PAR polymerizing enzyme (PARP) are more efficient in cells BRCA1 mutated with saved BARD1 tumor suppressor function." (PMID 29292755, 2017). "Immunogenic potential of the tumor suppressor BRCA1-associated RING domain 1 (BARD1) has been shown in a screen for antigens protecting against experimentally induced cancer in mice." (PMID 28786985, 2017). "Several scientific evidences show that cancer-associated BARD1 isoforms antagonize the functions of FL BARD1 as tumor suppressor and act as a driving force for carcinogenesis." (PMID 29292755, 2017). "Cancer-associated BRCA1-independent activities of BARD1 have been reported in various tumor cell lines." (PMID 29292755, 2017). "The tumor suppressor functions of BRCA1 are largely attributed to stabilization of BRCA1 by heterodimer formation with binding partners such as BARD1 within the BRCA1-associated RING domain protein." (PMID 27197561, 2016). "One prominent example is the BRCA1-associated protein BARD1, which establishes a causal link between mRNA 3′ end processing and tumor suppression." (PMID 27220521, 2016). "The E3 ligase activity of the BRCA1:BARD1 heterodimer is believed to be implicated in tumor suppression, as missense mutations in the RING domain of BRCA1 that disrupt the interaction with E2 have been reported in patients." (PMID 24695549, 2014). "Of note, rs17489363 at the BARD1 locus was found to be associated with predisposition to high-risk NB and correlated with low expression of full-length BARD1 which may act as tumor suppressor." (PMID 39843641, 2025). "However, the direct impact of these mutations on BARD1’s tumor suppressor function and their potential prognostic value requires further clarification." (PMID 41009605, 2025). "In addition to unearthing new insights into BARD1’s tumor suppressor function, we provide a comprehensive variant effect dataset that can be used to inform inherited cancer risk and treatment decisions." (PMID 41282735, 2025). "Since PGF expression increases locally in the tumor milieu upon PARPi treatment, it is possible that a minor subpopulation of Brca1- and Bard1-deficient tumor cells that express the PGF receptor FLT1 prior to PARPi treatment becomes enriched in the PARPi-resistant tumors." (PMID 38956205, 2024).